CDK4 (cyclin dependent kinase 4)
Diseases named in the same sentence as CDK4 in open-access papers (continued):
Sharing a sentence is not in itself a finding about the gene and the disease.
tumor (continued). "The CDK4 promotes tumor cell differentiation from G1 to S phase and increases proliferation." (PMID 34123852, 2021). "The triple combination-treated group contained significantly fewer metastasis (defined, approximately, as tumor area > 2500 μm2) compared to the combined fulvestrant and CDK4/6i-treated group at 6 weeks of treatment in both MPF-R (p = 0.050) and TPF-R (p = 0.042) models." (PMID 34433817, 2021). "Importantly, only patients with tumor types in which RB was functional were recruited to these trials, as CDK4/6 inhibitors rely on the de-repression of functional RB to inhibit E2F and cell cycle progression." (PMID 34025662, 2021). "Additionally, the increased tumor neoantigen observed after CDK4/6 blockade increases the efficacy of ICB." (PMID 34150632, 2021). "We next used western blot analysis to determine whether AK2 bound to endogenous CDK4 present within cell lysates of tumour cell lines HeLa and MCF-7 by conducting SDS-PAGE followed by transfer of isolated proteins to PVDF membranes." (PMID 34930213, 2021). "CDK4/6 inhibitor treatment promotes T cell-mediated anti-tumor immunity by different means." (PMID 34248938, 2021). "ESR1-MUT may selectively attenuate the efficacy of the anti-estrogen component of a combination regimen, and subsequent tumor response becomes dependent on sensitivity to the partner agent (CDK4/6i, PI3Ki, or mTORC1i)." (PMID 34392831, 2021). "The tumor equivocally stained for MDM2 and CDK4 and negatively for S100, with loss of H3K27me3." (PMID 33580196, 2021). "Furthermore, regulatory T cells (Tregs) are highly sensitive to CDK4/6 inhibitor-mediated anti-proliferative effects, which contributes to the enhanced tumor surveillance." (PMID 34248938, 2021). "In addition to inducing tumor cell cycl e arrest, mounting evidence reveals the immune modulatory of CDK4/6i in the TIM of BC." (PMID 33413549, 2021). "However, long‐term treatment with infigratinib resulted in the emergence of drug‐resistant tumour characterised by an increase in CDK4/Cdc2/Rb pathway." (PMID 33179425, 2021). "We observed that PDX KCC_P_3837-FPR mice treated with the triple combination showed a statistically significant (p = 0.003) increase in progression-free survival (PFS), with progression defined as tumor width ≥ 5 mm, compared to mice in the combined CDK4/6i and fulvestrant treatment group." (PMID 34433817, 2021). "In addition to their immune-potentiating effects, inhibitors of CDK4/6 can also dampen immunity via increased expression of PD-L1 on tumor cells." (PMID 34025662, 2021). "To verify whether GLI1 overexpression upregulates cell cycle regulators and the PI3K/AKT pathway in this model, we examined the expression of GLI1, p-AKT, Cyclin D3, CDK4, and Ki67 in the xenograft tumor tissues using immunohistochemical staining." (PMID 33658491, 2021). "In the interim, the immunomodulatory effects of CDK4/6 inhibitors are still being elucidated and additional pre-clinical studies are required to better understand how to most effectively use CDK4/6 inhibitors to boost anti-tumor immunity." (PMID 34025662, 2021). "Almost all EMPD samples (108/110, 98.2%) were positive for CDK4 staining (staining was defined as positive when at least some of the tumor cells were stained), and 98 of 110 (89.1%) EMPD samples were positive for cyclin D1 staining at various staining intensities." (PMID 34395284, 2021). "Therefore, targeting CDK4 allows the tumor population to shift to a more epithelial state, which would prime the tumor cells for MEK inhibitor treatment." (PMID 34309585, 2021). "CDK4/6i+ET combinations were the most effective treatment in the first-/second-line settings irrespective of tumor metastatic distribution and PIK3CA mutational status, as well as in endocrine-sensitive tumors." (PMID 33810205, 2021).
tumor (continued). "Moreover, the cell cycle is an essential factor of cell growth; the cell cycle is regulated by complexes of cyclins and cyclin-dependent kinases during cell division, Cyclin D1, CDK1, CDK2, and CDK4 are often upregulated in tumor cells." (PMID 33953676, 2021). "Such alterations of CDK4 gene expression can result in excessive activation of CDK4 kinase within tumour cells that, in turn, drives cell proliferative disorders that can trigger tumourigenesis of most tumour types." (PMID 34930213, 2021). "We next examined the levels of cyclinD1 and Cdk4 in shNT and shOrai3 tumor protein samples." (PMID 34885048, 2021). "However, the coadministration of a CDK4/6 inhibitor with anti-PD-1 immunotherapy enhanced tumor regression and increased overall survival in mouse cancer models." (PMID 34071228, 2021). "The results of this study provide evidence that a new promising anti-tumour treatment strategy, anti-CDK4 scFv, may be useful for tumour diagnosis and CDK4-targeting therapeutic applications." (PMID 34930213, 2021). "Next, we functionally validated the shRNA screen and determined whether response to CDK4 inhibitors is dependent on the EMT status of tumor cells." (PMID 34309585, 2021). "We found that in most cases, p16 showed a loss of expression in cartilage and dedifferentiated components, which may suggest that the inhibition of CDK4 and Cyclin D1 was reduced, prompting tumor cells to enter the cell cycle progression." (PMID 34631758, 2021). "We next tested the long-term effect of inhibiting CDK4 on the EMT status of tumor cells." (PMID 34309585, 2021). "We next evaluated in vivo tumor response to the combination of CDK4 and MEK inhibitors." (PMID 34309585, 2021). "While the majority of studies examining the immunomodulatory activity of CDK4/6 inhibition focused on tumor-intrinsic effects or effects on the tumor microenvironment more broadly, a seminal article in 2018 reported on the direct impact of CDK4/6 inhibition on T cells." (PMID 34025662, 2021). "Similarly, CDK4/6 inhibition, which suppress the activity of E2F targets, demonstrated to trigger anti-tumor immunity, thus uncovering a new function of E2F targets beyond the regulation of cell cycle." (PMID 34359727, 2021). "Importantly, the dual blockade of CDK4/6 and HSP90 is observed in Rb-deficient tumor cells suggesting a novel approach for cancer therapy." (PMID 34686682, 2021). "After we determined that AK2 could bind specifically and with high affinity to rhCDK4, we next tested whether AK2 could also bind to endogenous CDK4 within tumour cells." (PMID 34930213, 2021). "Likewise, antagonizing AR function in combination with CDK4/6 inhibition (abemaciclib) suppresses TNBC tumor growth, the direct opposite of that observed for luminal disease where AR agonism synergized with CDK4/6 inhibition (palbociclib) to block growth." (PMID 34680352, 2021). "Studies showed that CDK4/CDK6 inhibition promoted apoptosis in tumor cells." (PMID 32860670, 2020). "Therefore, CDK4/6 inhibitors combined with a PD-L1 immune checkpoint inhibitor can improve the effect of tumor immunotherapy." (PMID 33364954, 2020). "However, the SASP induced by CDK4/6 inhibitors is a double-edged sword in cancer treatment that can inhibit the growth of tumors but also promote tumor progression." (PMID 33116117, 2020). "In addition to the effective tumor shrinkage, co-targeting CDK4/6 and autophagy results in the activation of Bcl anti-apoptotic pathway post multiple i.v. injections." (PMID 32843618, 2020). "Besides the obvious effects on cell cycle arrest, the effects of CDK4/6 inhibition go well beyond and include induction of a senescence-like state and an improved tumor surveillance." (PMID 33255177, 2020). "In the initial stage of this study, we hypothesize that the main mechanism of anti-tumor activity of abemaciclib was growth inhibition like any other previously developed CDK4/6 inhibitors." (PMID 32899250, 2020).
tumor (continued). "Moreover, CDK4/6 inhibitors were found to increase tumor immunogenicity via RB1-dependent mechanisms." (PMID 32486375, 2020). "CDK4/6 inhibitors may play a role in inhibiting tumor growth by synergizing or antagonizing certain signaling molecule inhibitors and immune checkpoint inhibitors, which indirectly reflects their extensive antitumor effect." (PMID 32357912, 2020). "Besides, the miR-124/cyclindependent kinase 4 (CDK4) axis has been identified to decrease tumor aggression and aggravation, by triggering apoptosis in EC cell lines, which ultimately enhances radiotherapy efficiency." (PMID 32122355, 2020). "Herein, we found that ASPM ablation reduced the expression levels of CCND1 and CDK4, which may cause the disorder of LSCC cell cycle and further block cell proliferation and tumor development." (PMID 32742488, 2020). "The combination of CDK4/6 inhibitors and radiation may not only improve local tumor control but also enhance systemic disease control, providing the possibility for the triplet combination of CDK4/6 inhibitors, radiotherapy and immunotherapy." (PMID 32933570, 2020). "Collectively, CDK4/6 inhibitors and radiotherapy may synergistically exert an anti-tumor immune response by enhancing antigen presentation capacity and T cell activation." (PMID 32933570, 2020). "CDK4/6 inhibitors exert similar tumor-suppressing functions as Ink4 family members." (PMID 32933570, 2020). "In Zhang’s study, CDK4/6 inhibitor combined with PD-1 antibody significantly reduced the proliferation of tumor cells and improved the survival rate of carcinogenic mic e, illustrating the synergistic antitumor effect of the CDK4/6 inhibitor and immune checkpoint-related inhibitor." (PMID 32357912, 2020). "CDK4/6 inhibitors not only arrest the tumor cell cycle, but also trigger antitumor immunity." (PMID 32357912, 2020). "Based on our findings, it is possible that co-administration of inhibitors of MEK, PI3K, mTOR, IDH1, EZH2 or CDK4/6 (to target CDKN2A deletion) may have been effective in slowing or reducing tumour progression." (PMID 33053751, 2020). "Moreover, administration of wogonin and sunitinib also inhibited the expression of CDK4, p-RB, and Cyclin D1 in tumor tissues." (PMID 32792963, 2020). "Indeed, several investigators have demonstrated that CDK4/6 inhibitors exhibited direct immunostimulatory effects in both tumor and immune cells." (PMID 32933570, 2020). "Of note, the INK4 protein p16 can be induced by growth factor-β (TGFβ) signaling, and is able to bind to CDK4 and 6, decreasing cell progression from G1 phase to S phase, and therefore acting as a tumor suppressor, in opposition to the ER and CDK4/6 signaling stimuli." (PMID 32882980, 2020). "Other efficacy predictors include CDK4 phosphorylation and tumor cloning kinetics." (PMID 32357912, 2020). "Of those, the n‐terminal domain plays a key role in the inhibition of tumor growth through the P16/CyclinD/CDK4/RB/E2F pathway, during which dephosphorylation or hypophosphorylation of RB binds to intracellular transcription factor (E2F) and inhibits gene transcription." (PMID 32508051, 2020). "Thus, CDK4/6is have the potential to enhance the immune-mediated elimination of tumor cells when combined with immunotherapy." (PMID 32929370, 2020). "This may be the possible reason for CDK4/6 inhibitors enhancing anti-tumor immunity, as the cells in G1 phase show lower expression of both the immune suppressive proteins." (PMID 32961872, 2020). "In particular, we identified CNV in chr 12q leading to HMGA2/CDK4 upregulation, a high rate of SV in chr 7q leading to several in-frame gene fusions, a high rate of KMT2C mutation, and gene mutation signatures specifically related to MAS tumor progression." (PMID 32351899, 2020). "Parkin has been suspected to be a tumor suppressor: its expression increases oxidative metabolism, limits the Warburg Effect and regulates levels of cyclin D1, cyclin E and cyclin-dependent kinase 4 (CDK4) in cancers." (PMID 32548570, 2020).
tumor (continued). "Furthermore, SRX3177 was ~10–20-fold more potent than the CDK4/6 inhibitor palbociclib in these tumor cell lines." (PMID 32793389, 2020). "In contrast, our meta-analysis, as well as the previous ones confirms that the combination of CDK4/6 inhibitors and ET yields a very high rate of tumour regression, which is on average as high as 55% for patients with measurable disease, with no heterogeneity among different compounds." (PMID 32899139, 2020). "Accordingly, radiotherapy and CDK4/6 inhibitors may synergistically induce tumor cell senescence and further inhibit tumor progression." (PMID 32933570, 2020). "CDK4/6 inhibitors also induce cellular senescence and promote anti-tumor immunity, which might represent potential mechanisms for radiosensitization." (PMID 32933570, 2020). "Extensive cross-linking of CDK4/6 genes and key genes in classical tumor signaling pathways may exert synergistic or antagonistic effects, given the theoretical basis for CDK4/6 inhibitor combination therapy." (PMID 32357912, 2020). "CDK4/6 inhibitors are a novel class of selective cell cycle therapeutics that target the cyclin D-CDK4/6 complex and suppress activation of the downstream RB-E2F pathway, thereby blocking cell cycle progression and inhibiting the tumor cell proliferation." (PMID 32933570, 2020). "Interestingly, tumor cell senescence induced by CDK4/6i treatment shows a proinflammatory secretory phenotype, which is associated with increased lymphocyte infiltration 14,15." (PMID 32929370, 2020). "This cluster also enriched some well‐known stemness markers such as Sox11, Sox4, Nestin, Ptprs, and Cdk4, suggesting that they may function as the TICs in the tumor." (PMID 33173731, 2020). "Interestingly, in a recent study, a CDK4/6 inhibitor was tested in a set of 15 patients with various tumor types." (PMID 32198354, 2020). "Tumor growth was significantly inhibited in the CDK4/6i group compared with the control group." (PMID 32929370, 2020). "In primary malignant neoplasm of brain which including three DEGs (CDK4, EZH2, MYC)." (PMID 32696617, 2020). "In addition, CDK4/6 inhibitors enhance antitumor immunity by increasing T-cell activation and promoting T cells to kill tumor cells." (PMID 33364954, 2020). "The animal study for oral squamous carcinoma also revealed tumor stasis and cell cycle arrest in G0/G1 phase, associating with activation of AMP kinase pathway to decrease cyclin D1, cyclin-dependent kinase 4/6 (CDK4/6) and phosphorylated retinoblastoma protein." (PMID 31470817, 2019). "In addition, CDK4 expression in the primary tumor (formalin-fixed, paraffin-embedded tissues (FFPA) samples, n = 8) was higher in those patients that did not respond to therapy (p = 0.028)." (PMID 31817194, 2019). "In conclusion, our findings reveal that miR‐34b‐3p might function as a tumour suppressor in NSCLC by targeting CDK4 and that miR‐34b‐3p may, therefore, serve as a biomarker for the diagnosis and treatment of NSCLC." (PMID 31199581, 2019). "Previous studies have reported overexpression of CDK4/6 in multiple tumor types including OSCC." (PMID 30978209, 2019). "In theory, CDK4/6 inhibitors should be combined with cytotoxic agents that target the S or M phase of the cell cycle in order to capture tumor cells that may have escaped the cytostatic effects of CDK4/6 inhibition." (PMID 31600301, 2019).
tumor (continued). "It has been verified that CDK4/6 inhibition enhances the response to PD-1 blockade in an ex vivo organotypic tumor spheroid culture system; in vivo, CDK4/6 inhibition enhances tumor regression and markedly improves overall survival rates of murine syngeneic models." (PMID 30863749, 2019). "Thus, we reasoned that prospectively modeling the tumor evolution in response to a trastuzumab plus CDK4/6 inhibitor regimen will provide valuable insight to the potential acquired resistance mechanisms." (PMID 31444334, 2019). "While these mechanisms of resistance and their relevance in the clinic are currently being examined, a few key questions arise—Do these resistance mechanisms alter ER-driven tumor growth, and does an ER-targeted agent continue to be effective in patients with prior CDK4/6i therapy?" (PMID 31852484, 2019). "It is attractive to speculate that CDK4/6 regulates additional pro-angiogenic factors in the tumor microenvironment including macrophages or NK cells." (PMID 30858922, 2019). "Furthermore, blocking both EGFR/HER2 signaling and cell cycle transition through the combinatory regimen of anti-EGFR treatment and CDK4/6 inhibitors successfully hindered TNBC tumor progression." (PMID 31253784, 2019). "Cyclin-dependent kinase 4 and 6 (CDK4/6) inhibitors are another example of targets whose anti-tumor effect might be partially attributed to modulation of the immune system." (PMID 31817861, 2019). "Notably, despite the clinical benefits of CDK4/6 inhibitors, tumor resistance is developing in the metastatic patients and the mechanisms for this resistance are not clear." (PMID 31632494, 2019). "Inhibitors of CDK4/6 have been shown to have significant activity against several solid tumors, increase intracellular double-stranded RNA levels, and activate endogenous retroviral elements to inhibit tumor cell expression." (PMID 32117430, 2019). "We were also intrigued by the fact that CDK6 but also CDK4 interfered with tumor angiogenesis." (PMID 30858922, 2019). "Since the activity of the adaptive immune cells can be regulated by the innate counterpart, it may be important to carefully examine the consequence of CDK4/6 inhibition on innate immune cells such as macrophages and dendritic cells in tumor microenvironment." (PMID 30863749, 2019). "Gene expression levels measured relative to the adjacent normal cortex sample revealed numerous oncogenic driver genes with >2-fold higher expression in the tumour and clone samples, including genes encoding AURKA/B, CDK4/6, FGFR1, AKT1/2, MTOR, MET, PIK3C2A, WNT5A, SFRP4, and MYC." (PMID 30736342, 2019). "Furthermore, the expression of CyclinD1 and CDK4 was significantly lower in tumor tissues from zoledronic acid-treated mice than in tumor tissues from control mice." (PMID 30791957, 2019). "Therefore, blocking CDK4/6 activity on T cells facilitates the cytotoxic activity of T cells to kill tumor cells." (PMID 30863749, 2019). "Among these genes, CDK4, CCT2, and MGAT1 were associated with overall survival and recurrence-free survival, and the expression levels of these three genes were significantly higher in tumor tissues." (PMID 32117430, 2019). "Recently, senescence induced by CDK4/6 inhibition has also been shown to promote the development of cancer stem-like cells, leading to attenuated response to cytotoxic agents and tumor recurrence." (PMID 31600301, 2019). "Alterations in immune-related signaling pathways suggest that CDK4/6 inhibitors may affect the cellular immune system, thus affecting the efficacy of immunotherapies to tumor." (PMID 31358010, 2019). "Importantly, our findings indicate that combined pharmacological inhibition of MET and CDK4/6 is a feasible strategy able to improve tumour growth inhibition in mice, indicating the potential of this combination for clinical use." (PMID 31296956, 2019). "RNA-seq analysis showed that CDK4 inhibitors may affect tumor proliferation through multiple signaling pathways." (PMID 31358010, 2019).